UNC45B (unc-45 myosin chaperone B)
Description:
Acts as a co-chaperone for HSP90 and is required for proper folding of the myosin motor domain. Plays a role in sarcomere formation during muscle cell development. Is necessary for normal early lens development.
Synonyms: Unc-45B; CMYA4; UNC45; CTRCT43; MFM11; SMUNC45
Tractability: No criterion of Open Targets' tractability assessment is met for any kind of drug.
Gene: Protein-coding gene on chromosome 17 (35,146,495 to 35,189,346, forward strand). Ensembl gene ENSG00000141161.
Subcellular location: Cytoplasm, myofibril, sarcomere, Z line; Cytoplasm, myofibril, sarcomere, A band; Cytoplasm, perinuclear region; Cytoplasm, cytosol
Subcellular location (Human Protein Atlas): Cytosol
Gene Ontology:
Molecular function: protein binding; Hsp90 protein binding
Biological process: lens development in camera-type eye; protein folding
Cellular component: cytoplasm; A band; cytosol; perinuclear region of cytoplasm; Z disc
Genetic constraint (gnomAD): Loss-of-function variants: 76 observed, 94.94 expected, observed/expected ratio (o/e) 0.8, 90% interval 0.66 to 0.97. The upper end of that interval is the gene's LOEUF score, 0.97, which puts it in group 4 of 6, group 1 being the genes least tolerant of losing a copy. Missense variants: 1,221 observed, 1,197.7 expected, observed/expected ratio (o/e) 1.02, 90% interval 0.97 to 1.07. Synonymous variants: 462 observed, 483.35 expected, observed/expected ratio (o/e) 0.96, 90% interval 0.88 to 1.03.
Homologues: Orthologues: chimpanzee UNC45B (99% identical), macaque UNC45B (99% identical), dog UNC45B (97% identical), rabbit UNC45B (97% identical), pig UNC45B (96% identical), mouse Unc45b (95% identical), guinea pig UNC45B (95% identical), rat Unc45b (95% identical), tropical clawed frog unc45b (78% identical), zebrafish unc45b (71% identical), Drosophila melanogaster unc-45 (35% identical), Caenorhabditis elegans unc-45 (32% identical). Paralogues in human: UNC45A (57% identical), SPAG1 (11% identical), RPAP3 (10% identical), TTC12 (10% identical), STIP1 (9% identical), TOMM34 (9% identical), SPATA16 (8% identical), TOMM70 (8% identical), DNAAF4 (7% identical), ST13 (7% identical), SUGT1 (7% identical), TTC4 (6% identical), and 6 more.
Diseases named in the same sentence as UNC45B in open-access papers:
UNC45B is named in the same sentence as 26 diseases in open-access papers, as found by Europe PMC text mining. Sharing a sentence is not in itself a finding about the gene and the disease. The quoted sentences say what the papers report.
cardiomyopathy (5 papers, 2011 to 2025). A disease of the heart muscle or myocardium proper. "The variant in UNC45A was associated with cardiomyopathy (p=0.036) in FinnGen and the variant in UNC45B was associated with heart failure (p=0.049)." (PMID 38848015, 2024). "In humans, Unc45b is a candidate locus for cardiomyopathies and a protein determining hereditary inclusion-body myopathy (p97) regulates Unc45b stability." (PMID 23144999, 2012). "Importantly, in addition to cilia-associated genes, we identified recessive variants in four genes previously implicated in cardiomyopathy (MYH6, UNC45B, MYO18B, and MYBPC3) that are expressed in embryonic cardiomyocytes; RGs in these genes contributed to left-sided CHD phenotypes." (PMID 40030011, 2025).
congenital myopathy (2 papers, 2019 to 2021). "In conclusion, we here report for the first time a patient with an UNC45B mutation causing a novel genetically defined congenital myopathy disease entity." (PMID 31852522, 2019).
aortic stenosis (1 paper, 2025). Aortic valve stenosis is a aortic valve disease caused by the incomplete opening of the aortic valve. "All three probands with UNC45B RGs had left-sided heart defects that included aortic stenosis or bicuspid aortic valve as part of complex CHD." (PMID 40030011, 2025).
asthma (1 paper, 2019). "UNC45B, annotated to cg00100703, lies within the asthma susceptibility region 17q12–21, though this particular gene has not previously been linked to asthma." (PMID 31367216, 2019).
breast tumor (1 paper, 2017). "KANSL1 has also been reported fused with ORMDL3 and LAYN in one breast tumor and with UNC45B in one lung tumor." (PMID 28423358, 2017).
heart failure (1 paper, 2024). Inability of the heart to pump blood at an adequate rate to meet tissue metabolic requirements.
myofibrillar myopathy (1 paper, 2025). "UNC45B is associated with myofibrillar myopathy through recessive inheritance (OMIM# 619178)." (PMID 40030011, 2025).
myopathies (4 papers, 2015 to 2024). "We found evidence for 31/50 chaperones, including 17 chaperones that were associated with muscle diseases (e.g., HSPB8 with myopathies) and 27 chaperones that were associated with muscle function (e.g., the myosin chaperone UNC45B)." (PMID 33846299, 2021). "The transcriptional up-regulation of unc45b, hsp90aa1.1 and smyd1b is specific to zebrafish mutants with myosin folding defects, and is not triggered in other zebrafish myopathy models." (PMID 26631063, 2015).
UNC45B also shares sentences with these, for which no sentence is quoted: Arrhythmia (2 papers); cardiac diseases (2); amyloidosis (1); cardiac arrest (1); cardiac arrhythmia (1); cardiac hypertrophy (1); cataract (1); co-infection (1); dilated cardiomyopathy (1); Freeman-Sheldon syndrome (1); frontotemporal dementia (1); metastatic disease (1); neuromuscular genetic disease (1); ovarian carcinoma (1); Paget disease of bone (1); pancreatic cancer (1); sarcopenia (1); tumour (1).